Y_RNA (Y RNA )
Gene: Miscellaneous RNA gene on chromosome 1 (111,446,798 to 111,446,908, forward strand). Ensembl gene ENSG00000199890.
Homologues: Orthologues: chimpanzee Y_RNA (99% identical). Paralogues in human: RNY1 (91% identical), Y_RNA (91% identical), Y_RNA (90% identical), Y_RNA (88% identical), RNY1P11 (87% identical), Y_RNA (87% identical), Y_RNA (86% identical), RNY1P8 (85% identical), Y_RNA (85% identical), RNY1P10 (84% identical), RNY1P13 (84% identical), Y_RNA (84% identical), and 98 more.